NUDT1 (nudix hydrolase 1)
Diseases named in the same sentence as NUDT1 in open-access papers (continued):
Sharing a sentence is not in itself a finding about the gene and the disease.
cancer (103 papers, 2014 to 2025). A tumor composed of atypical neoplastic, often pleomorphic cells that invade other tissues. "Here, the authors show that nudix hydrolase 1 (NUDT1) is a MYC-driven metabolic vulnerability and generate a NUDT1 protein degrader to treat preclinical MYC-associated cancer." (PMID 38493213, 2024). "Overexpression of NUDT1 in cancer cells makes them more susceptible to carboplatin and triethylenemelamine, and cancer cells expressing higher levels of EIF4A1 were more sensitive to cladribine." (PMID 37089261, 2023). "Several researchers have found that NUDT1 deficiency in certain cancer cell lines caused by small RNA interference or genome editing does not result in any adverse effect on these cells." (PMID 36606241, 2022). "Cancers can survive the oxidative conditions by upregulating nucleoside diphosphate linked moiety X-type motif 1 (NUDT1)." (PMID 29075149, 2017). "However, the mechanism underlying the dys-regulation of NUDT1 in cancer, particularly in GC remains unknown." (PMID 29075149, 2017). "Having studied 526 of RCC samples from a TCGA database, the authors confirmed that the overexpression of NUDT1 in RCC cancer was correlated with clinicopathological features." (PMID 40507948, 2025). "The overexpression of NUDT1, detected in almost all cancer types studied, indicates an important role for this enzyme in cancer development and progression." (PMID 40507948, 2025). "NUDT1, or nudix hydrolase 1 or MutT Homolog1 (MTH1), has been paid attention in human research for its enzymatic activity associated with cancer." (PMID 40733408, 2025). "Further analyses involved two RCC cell lines, 786-O and ACHN, using siRNA to investigate the impact of NUDT1 knockdown on cancer cells." (PMID 40507948, 2025). "The results of each method confirmed the increase in NUDT1 levels in cancer tissues relative to normal tissues." (PMID 40507948, 2025). "Apoptosis increased in the silenced cells, confirming the conclusion that NUDT1 expression in RCC cells is crucial for cancer progression." (PMID 40507948, 2025). "All these data support that NUDT1 expression is required to sustain tumor cell survival in both mouse and human cancers that rely on MYC(N) hyperactivation." (PMID 38493213, 2024). "NUDT1 expression was positively correlated with carboplatin and triethylenemelamine sensitivity in cancer cells." (PMID 37089261, 2023). "Similar to NUDT18, NUDT1 is a major cleanser of the cytosolic pool of oxidized nucleotides and has been studied as a potential target in several cancer entities." (PMID 38134284, 2023). "The oxidative stress induced miR-361-3p/NUDT1 axis is first introduced in microbiome-carcinoma research." (PMID 37848855, 2023). "The oxidative stress mediated miR-361-3p/NUDT1 axis was introduced and validated in this microbiome-carcinoma research." (PMID 37848855, 2023). "It has been reported that NUDT1 is overexpressed in various cancers, including cancers of the bladder, breast, colon, and kidney." (PMID 36606241, 2022). "It was shown that cancer cells require NUDT1 to sanitize oxidized dNTP, preventing DNA damage and cell death caused by the incorporation of oxidized dNTP." (PMID 36036011, 2022). "Based on TCGA-KIRC cohort, we explored the relationship between NUDT1 and cancer immune infiltrates at the mRNA level." (PMID 36606241, 2022). "The discovery of NUDT1 first aroused the interest of carcinogenesis investigators owing to its role in maintaining genomic stability, which is often compromised during cancer development." (PMID 36606241, 2022). "It indicates that NUDT1 plays an indispensable role in surviving the oxidative stress in cancer cells." (PMID 36606241, 2022). "As a member of the Nudix hydrolase superfamily, Nudix (nucleoside diphosphate-linked moiety X)-type motif 1 (NUDT1) is closely related to the occurrence and development of cancer." (PMID 36606241, 2022).
cancer (continued). "In the same study, NUDT1 inhibition by small molecules was validated to suppress cancer growth by accumulating oxidative damage." (PMID 36036011, 2022). "The use of cellular models of RAS-dependent cancers has driven the identification of molecule 49 (SCH51344) as a human mutT homolog MTH1 (also known as NUDT1) inhibitor, a nucleotide pool sanitizing enzyme." (PMID 35408636, 2022). "The oxidative stress pathway inhibited by the high expression of NUDT1 plays an important role in the cancer‐promoting of HIF2α in ccRCC." (PMID 34841698, 2021). "Dozens of NUDT1 inhibitors have been developed with the goal of inhibiting cancer growth by accumulating oxidative damage in cancer cells." (PMID 34841698, 2021). "NUDT1 protects the nucleic acid of cancer cells from oxidative damage by removing excess 8‐oxo‐dGTP." (PMID 34841698, 2021). "Overexpressed NUDT1 promotes cancer cell growth and metastasis by reducing ROS levels and hydrolysing ROS products, such as 8‐oxo‐dGTP." (PMID 34841698, 2021). "MTH1 (MutT homolog 1) or NUDT1 (Nudix Hydrolase 1), also known as oxidized purine nucleoside triphosphatase, has potential as a biomarker for monitoring cancer progression and quantifying target engagement for relevant therapies." (PMID 33238630, 2020). "Incorporating damaged dNTPs in cancer cells has been suggested as a strategy to increase replication stress by targeting NUDT1 (MTH1), which prevents misincorporation of oxidized dNTPs during replication." (PMID 32854236, 2020). "Polymorphisms of MLH1, APEX1, MUTYH, OGG1, NUDT1, and XRCC5 are associated with sporadic CRC and other site‐specific cancers." (PMID 29664240, 2018). "Our findings provide evidence for the function of miR-485-5p in GC and can clue to the treatment by targeting NUDT1 in cancer." (PMID 29075149, 2017). "MiR-485-5p was verified to be an upstream regulator of NUDT1, and the dramatic knock-down of miR-485-5p in GC leads to upregulation of NUDT1, thus contributing to accelerated proliferation and increased migration of cancer cells." (PMID 29075149, 2017). "NUDT1, acts as a nucleotide pool sanitizing enzyme, plays an indispensable part in surviving the oxidative stress in cancer cells." (PMID 29075149, 2017). "To conclude, experimental evidence in our study proves that miR-485-5p possesses a tumor-suppressive function in GC and the down-regulated miR-485-5p lead to the increased expression of NUDT1, thus contributing to cancer progression." (PMID 29075149, 2017). "And some positive correlations have been observed between the expression levels of NUDT1 and the prognosis of cancer patients." (PMID 29075149, 2017). "In cancer cell lines, the mRNA levels of NUDT1 were 3- to 25-fold higher compared to HMSC cells." (PMID 40507948, 2025). "However, only a few enzymes or metabolites in this pathway are invariably over-expressed across cancers (e.g., NUDT1, LEF1, 9H-xanthine)." (PMID 38723607, 2024). "Here we highlighted the important role of oxidative stress in the mechanism of Fn-carcinoma and how NUDT1-related autophagy may play a role in the progression of HPSCC." (PMID 37848855, 2023). "This suggests that the downregulation of NUDT1 may diminish the sensitivity to ROS in carcinoma cells." (PMID 37848855, 2023). "Both CCK-8 assays and EdU assay suggested that decreasing NUDT1 could inhibit the proliferation of carcinoma cells, even when infected with Fn." (PMID 37848855, 2023). "Considering the reasons of NUDT1 based on HIF2α knockdown and oxidative stress screening, as well as the important characteristics of NUDT1 as a cancer‐promoting gene, we have reason to believe that NUDT1 has a potentially key role in the cancer‐promoting pathway of HIF2α." (PMID 34841698, 2021). "Above research results indicate that NUDT1 may be an important potential downstream of HIF2α in promoting cancer in ccRCC, so the specific regulatory mechanism between them has become the focus of this unit." (PMID 34841698, 2021).
cancer (continued). "The original interest in pharmacological modulation of NUDIX members was sparked by the notion that NUDT1 is overexpressed in several cancer cell types, while its role in healthy cells can largely be compensated for as evidenced by the normal life-span of knock-out mice." (PMID 32548091, 2020). "As a result, cancer cells up-regulate NUDT1 to eliminate excessive 8-oxo-dGTP, indicating that increased expression of NUDT1 in cancer cells may be detrimental for cancer patients." (PMID 29075149, 2017). "It has been reported that NUDT1 is overexpressed in various cancers." (PMID 29075149, 2017). "However, a distinct cluster appeared when comparing cancer vs normal tissues, which contained NUDT1, NUDT5, NUDT8, NUDT14, and NUDT22, confirming a potential role of these NUDIX hydrolases in cancer." (PMID 29142246, 2017). "Indeed, two previous investigations have posited NUDT1 as a universal target for cancer therapies based on the observations that knockdown of NUDT1 expression or small chemical inhibition of its activity selectively induced tumor cell death without affecting normal cells." (PMID 38493213, 2024). "Although there are differences between different normal and tumour samples, which may reflect the heterogeneity of patient tissues, the expression of NUDT1 in tumours is consistent with HIF2α and both are upregulated compared to normal tissues adjacent to cancer." (PMID 34841698, 2021). "This led to the hypothesis that increased expression of NUDT1, and hence improved sanitization capacity of oxidatively damaged DNA bases from the nucleotide pool, would enable cancer cells to cope with the increased oxidative stress they are exposed to compared with healthy cells." (PMID 32548091, 2020). "The Human MutT Homolog 1 (MTH1, Nudix hydrolase 1, NUDT1) protein is overexpressed in various cancer types." (PMID 40806307, 2025). "However, later independent studies failed to reproduce these results (arguing that the prior observations could be due to the off-target effects of NUDT1 siRNAs and/or small chemical inhibitors), challenging the notion of NUDT1 as a feasible, universal target for cancer therapy." (PMID 38493213, 2024). "To facilitate the clinical transformation of the five genes model, we further identified FDA-approved sensitive drugs that express high levels of CYFIP2, EIF4A1, NUDT1, NUDT4, and NUDT10 in multiple cancer cell types." (PMID 37089261, 2023). "NUDT1, NUDT5, and NUDT14 are highly expressed in cancers, indicating a potential role of these NUDIX enzymes in cancer." (PMID 35168561, 2022). "The increased expression of WDR4, METTTL1, NUDT1, and CYFIP2 enhanced the sensitivity of some anti-cancer drugs such as hydroxyurea, L-asparaginase, 5-fluoro-deoxy-uridine 10mer, and chelerythrine." (PMID 36226166, 2022). "NUDT1, NUDT5, and NUDT14 belong to the cluster of highly expressed NUDIX in cancer, pointing toward a potential role of these NUDIX enzymes in cancer, which has been previously proposed." (PMID 29142246, 2017). "The expression of MTH1, also known as NUDT1, is upregulated in multiple types of digestive tract tumors, and high MTH1 expression promotes the survival of tumor cells but not normal cells, making MTH1 a potential target for cancer treatment." (PMID 39075342, 2024). "Although these NUDT1 inhibitors have been shown to be effective in suppressing cancer, some studies have pointed out that NUDT1 inhibitors have failed to completely eradicate cancer cells." (PMID 34841698, 2021). "Interestingly, NUDT1, NUDT5, and NUDT14 amongst others were present in a cluster of highly expressed proteins, confirming a potential role in cancer." (PMID 32548091, 2020). "Based on the protective properties of NUDT1 against oxidative stress in cancer cells and the nonessential role of it in normal cells, NUDT1 inhibitors have been developed as potential anti-cancer drugs." (PMID 29075149, 2017). "Our results showed that NUDT1 is not a general target for cancer treatment." (PMID 38493213, 2024).
cancer (continued). "Given that a major hurdle in cancer treatment is the need to pinpoint the subset(s) of patients who might benefit from any emerging targeted therapy, we propose that MYC(N) hyperactivation might become a useful predictive biomarker in NUDT1-based treatment regimen." (PMID 38493213, 2024). "However, NUDT1 may not be always indispensable for cancer cell survival under oxidative conditions." (PMID 36606241, 2022).
tumor (78 papers, 2013 to 2025). "F. nucleatum enriched in tumor tissues and associated with worse prognosis and promoted oxidative stress via the miR‐361‐3p/NUDT1 axis." (PMID 41216129, 2025). "Ischemia very interestingly appears to slowly breach through this coping mechanism by causing a decrease in tumor survival-critical proteins such as NUDT1, ELOVL5, HPGDS or DZIP3." (PMID 39327466, 2024). "As expected, NUDT1 inhibition induced significant cell death in all the tumor cells associated with MYC/MYCN overexpression, whereas those with low MYC/MYCN levels exhibited minimal cell death, underscoring the association between MYC overexpression and NUDT1 dependency." (PMID 38493213, 2024). "After conducting the GSEA analysis, several pathways related to tumor formation regulated by NUDT1 were identified, including fatty acid metabolism, cell cycle, bile acid and bile salt metabolism, and the PLK1 signaling pathway." (PMID 40507948, 2025). "A strong positive correlation was found between high levels of NUDT1 and histopathologic tumor grade and tumor stage, as well as poor prognosis of survival." (PMID 40507948, 2025). "These mutations correlate with a tumor mutation load more than five times higher than in tumors with wild-type PMS2, The PMS2 and MTH1/NUDT1 genes are closely located on chromosome 7 (at 7p22.1 and 7p22.3, respectively)." (PMID 38357002, 2024). "Given MYC(N)-overexpressing tumor cells strictly rely on NUDT1 to sanitize oxidized nucleotides for viability, we postulated that NUDT1 expression and/or catalytic activity should be enforced to adapt to MYC(N)-driven metabolic reprogramming." (PMID 38493213, 2024). "Instead, we found that MYC(N)-high tumor cells and tumor models in vivo were addicted to NUDT1 function." (PMID 38493213, 2024). "MutT homologue-1 (MTH1, also known as NUDT1), a member of the Nudix family, maintains the genomic integrity and viability of tumor cells in the hypoxic tumor microenvironment." (PMID 39272872, 2024). "The result of Transwell assay also showed that knockdown of NUDT1 reduced the migration and invasion of tumor cells." (PMID 37086071, 2023). "Previous studies have demonstrated that NUDT1 is more crucial for tumor cells than nomal cell to alleviate high intracellular ROS levels, particularly 8-oxo-dG." (PMID 37848855, 2023). "Cell migration analysis showed that knockdown of NUDT1 significantly reduced the migration of tumor cells after transfection." (PMID 37086071, 2023). "From the CCK-8 experiment, we found that NUDT1 promoted tumor cell proliferation at 24, 48 and 72h after transfection." (PMID 37086071, 2023). "NUDT1 negatively correlated with survival, and further analyses revealed that knockdown of NUDT1 inhibits proliferation and migration of tumor cells." (PMID 35096203, 2022). "TCGA dataset and Tumor IMmune Estimation Resource (TIMER) database were utilized to explore the relationship between NUDT1 and immune infiltration." (PMID 36606241, 2022). "Cox proportional hazards regression model indicates that NUDT1 expression in tumor cells is an independent prognostic indicator of ccRCC." (PMID 36606241, 2022). "Through the evaluation of subcutaneous transplanted tumours in nude mice, it is found that knocking down NUDT1 can significantly inhibit the growth rate of tumours." (PMID 34841698, 2021). "To verify the regulatory effect of silencing NUDT1 on oxidative stress, we detected the levels of 8‐oxodG and protein carbonylation in subcutaneous tumour tissues in nude mice." (PMID 34841698, 2021). "Our study describes a new approach, HIF2α reduces the biological effects of oxidative stress in tumour cells through NUDT1." (PMID 34841698, 2021).